STAT2 (signal transducer and activator of transcription 2)
Diseases named in the same sentence as STAT2 in open-access papers (continued):
Sharing a sentence is not in itself a finding about the gene and the disease.
infection (continued). "Noticeably, NH/P68 infection was also able to impair STAT2 expression through a similar mechanism." (PMID 34512601, 2021). "Furthermore, a gradual up-regulation of IRF7, IRF9, STAT1 and STAT2 genes was observed in Calu-3 cells after the infection with SARS-CoV-2 for 24 h." (PMID 34578229, 2021). "Interestingly, we observed a decrease in ISG expression in brachial lymph nodes of xeno mice 2 days following infection, with Ifi44, Irf7, and Stat2 mRNA levels reduced." (PMID 33031404, 2020). "Moreover, genes such as Ifr9, Ifr8, Ifr7, CSF2RA, STAT1, and STAT2 were expressed to a greater extent in the PmQ infection group than PmCQ2, and Il22, Il6, Nos2, Ccl4, Ccl5, Ifr1, Socs1, and Socs3 were increased only in PmQ infected chickens rather than PmCQ2." (PMID 32851030, 2020). "To address whether the extent of pathway sensitization is cell type‐specific, we examined Roferon‐induced phosphorylation of STAT1 and STAT2 in the nucleus of HepG2‐hNTCP cells, which are commonly used to study infection of hepatitis B virus." (PMID 32696599, 2020). "Similarly, Irf7, Isg15 and Stat2 mRNA levels were decreased in axillary lymph nodes of xeno mice 7 days post-infection relative to control mice." (PMID 33031404, 2020). "In contrast to STAT1-deficient mice, mice that lack STAT2 do not develop lethal disease after IP or IC infection with LCMV-Arm, despite both mice showing uncontrolled viral replication and spread." (PMID 30791575, 2019). "Interestingly, in macrophages, the expression of total IRF3 or STAT2 protein levels seemed to be reduced at 2 and 6 h after infection with both types of viruses." (PMID 31673117, 2019). "Interestingly, in macrophages we observed host protein degradation, especially IRF3 and STAT2, at early phases of infection with both lineage viruses, suggesting an early proteasomal activation in phagocytic cells." (PMID 31673117, 2019). "Together, these data suggest that in the absence of STAT2, there is alteration of other associated signaling pathways during super-infection." (PMID 30337919, 2018). "STAT2-deficient mice were similarly susceptible to ΔM27-MCMV and wt-MCMV infection: within 1 week, most infected STAT2-deficient animals succumbed to infection irrespective of the presence or absence of pM27." (PMID 29743368, 2018). "We analyzed infections caused by MCMV expressing or lacking the STAT2 antagonist pM27 in STAT2-deficient and control mice to evaluate its importance for the host and the virus in vitro and in vivo." (PMID 29743368, 2018). "In addition, we also evaluated viremia and viral RNA levels in the brain and ovaries of Stat2-/- mice on days 2, 4 and 6 post infection." (PMID 28278235, 2017). "In contrast, expression of other genes in the IFN signaling pathway (G1p2, Ifi35, Ifit1 and Stat2) were shown to be higher in the infected WT as compared to the infected Ifnar1-/- mice after days 2 and 3 of infection, when the bacterial load was lower in the infected Ifnar1-/- mice." (PMID 26918359, 2016). "Since PML interacted with STAT1, STAT2, HDAC1, and HDAC2, we investigated whether IE1 simultaneously interacts with PML, STAT1, STAT2, and HDACs during infection." (PMID 25812002, 2015). "Components of interferon pathway and innate immunity (IFI44L, IFITM3, MX1, IRF7, OAS2, STAT2, etc.)are significantly upregulated in the acute phase of infection, while the expression levels of genes involved in translational elongation and protein biosynthesis are decreased." (PMID 26070066, 2015). "Likewise, DDB1 ablation fully restored STAT2 amounts 4 h post infection (lane 4) and partially after 24 h (lane 10)." (PMID 21698215, 2011). "On the contrary, the phosphorylated forms of STAT1 and STAT2 that were induced by MPRV infection could still be detected more than 24 h p.i., which would seem to suggest that these forms are stabilized in MPRV-infected cells." (PMID 17325370, 2007).
infection (continued). "Protein–protein interaction network analysis identified several hub genes (Usp18, Stat2, Ifih1, Jun, Irf7, Rsad2, Ifit1, Mx1) that likely play central roles in coordinating the antiviral immune response and immunometabolic regulation across different phases of infection." (PMID 40867782, 2025). "In contrast, infection susceptibility is not a primary feature of STAT2 “GOF”, although it may occur along the disease course, either as a trigger for subsequent hyperinflammation or in the context of pre-existing critical illness." (PMID 39599507, 2024). "Infection with both KUNV (a WNV variant) and NY99 strain of WNV prevents the translocation of STAT1 and STAT2 from the cytoplasm to the nucleus by inhibiting the STAT1 and STAT2 phosphorylation in response to IFN treatment, and it is also able to downregulate STAT1 expression." (PMID 34338586, 2021). "Notably, favipiravir has been confirmed to provide a complete protection against the lethal SFTSV infection for Stat2–/– hamsters in accord with the conclusion drawn from Ifnar–/– mice, while ribavirin that provides protection for Ifnar–/– mice is ineffective for Stat2–/– hamsters against SFTSV." (PMID 35087498, 2021). "Interestingly, both STAT1 and STAT2 degradation are less pronounced during NH/P68 infection, which could help to explain at least in part the low virulence pattern observed in pigs after infection with this attenuated ASFV strain." (PMID 34512601, 2021). "In addition to affecting the outcome of infection, STAT2 also regulates DC expansion." (PMID 30791575, 2019). "When we investigated the bacterial burdens at 48 hours post infection, the time point where we observed changes in immune responses, we found that there were significantly fewer bacteria in the cecum and colon contents of Stat2-/- mice compared to wild-type mice." (PMID 31009517, 2019). "However, the increase in MCMV titers and the kinetics of disease progression in STAT2-deficient mice taking place in the first week after infection do not argue for an impairment of adaptive immunity." (PMID 29743368, 2018). "However, total STAT2 levels increased independently of infection over time in CD46+ explants." (PMID 27178303, 2016). "Consistently, immunoblotting analysis indicated that infection of LSDVΔ122 resulted in higher STAT1 and STAT2 phosphorylation upon IFN-β stimulation than wild-type LSDV." (PMID 41525414, 2026). "Upon infection with A/WSN/33 or interferon treatment, A549 cells show increased phosphorylation of STAT1, STAT2, and NF-κB." (PMID 40434103, 2025). "The PRV UL41 protein, as well as the mRNAs of JAK1, Tyk2, STAT1, STAT2, and IRF9, were detectable in the RIP mixture, signifying that the mRNAs of JAK1, Tyk2, STAT1, STAT2, and IRF9 are among the targets of PRV UL41 during infection." (PMID 41341288, 2025). "Compared with ASFV-Δ4R infection, ASFV-WT infection consistently decreased the binding of STAT1, STAT2 and IRF9." (PMID 40618140, 2025). "Consistently, compared with infection with ASFV-WT, infection with ASFV-Δ4R increased nuclear translocations of phosphorylated STAT1, phosphorylated STAT2, and IRF9 in PAMs." (PMID 40618140, 2025). "As expected, compared with the ASFV-WT strain, ASFV-Δ4R infection increased phosphorylation of STAT1 and STAT2 and subsequent ISGF3 formation, leading to an elevated expression of antiviral gene ISGs." (PMID 40618140, 2025). "Viral replication did not alter IFNAR expression but led to reduced phosphorylation of STAT1, as well as both degradation and reduced phosphorylation of STAT2, similarly to DENV-infection." (PMID 41477009, 2025). "Both Western blot and grayscale analysis showed that ARCN1 knockdown markedly increased IKKε protein abundance upon infection, accompanied by elevated phosphorylation of IRF3, STAT1, and STAT2." (PMID 41343552, 2025).
infection (continued). "Of note, the cultures cluster derived from XX T21-12 specimen, which had lowest infection level, has consistently the highest STAT1 and STAT2 expression, corresponding to the highest MX1 expression." (PMID 40445428, 2025). "Comparing infection-induced TCRab+ T cells, adults exhibited higher average STAT3, SOCS1, and SOCS3 expression, whereas STAT1 and STAT2 were elevated in cells from infected children, highlighting divergent IFN signaling with age." (PMID 40834853, 2025). "On the other hand, in the pre-infection assays with C. sorokiniana, the mRNA levels of SOCS3 and IFN-γ were increased, whereas in the post-infection assays, SOCS3, STAT1, and STAT2 were upregulated." (PMID 38791551, 2024). "3Cpro utilizes its protease activity to cleave STAT1 and STAT2, thereby diminishing the host IFN response to promote SVA infection." (PMID 38869319, 2024). "We found that ASFV-WT infection significantly reduced the phosphorylation and nuclear translocation of STAT1 and STAT2 induced by IFN-α." (PMID 38620034, 2024). "We identified important genes DE in both our in vitro and in vivo infection models consistent with previous studies, namely, TLR3, IFIH1 (MDA5), SOCS1, OASL, DDX60, STAT1, MX1, CMPK2, LY96 (MD-2), STAT1, STAT2, TRIM25, IRF7, and IFIT5." (PMID 38675946, 2024). "ASFV-intB318L infection also obviously suppressed the phosphorylation and nuclear translocation of STAT1 and STAT2; the inhibitory effect was significantly lower than that of ASFV-WT infection." (PMID 38620034, 2024). "Given the pivotal roles of STAT1 and STAT2 in the IFN response signaling pathway, viruses have evolved various means to subvert their functions for establishing infection." (PMID 38869319, 2024). "While GBP2 induction in MRC5 cells infected with 229E or OC43 infection was lower than those stimulated with IFN-γ, the expression levels of RIG-I and STAT2 induced by 229E or OC43 infection were similar to those induced by IFN-α or -γ stimulation." (PMID 37197656, 2023). "Highly activated TFs include STAT1, STAT2, and IRF3, which are responsible for innate and acquired immune responses and host defenses against infection." (PMID 38042877, 2023). "In contrast, OC43 infection induced all IFN-inducible genes tested at 2 days after infection, and the expression levels were significantly higher than control at 4 days except for GBP2 and STAT2." (PMID 37197656, 2023). "Accordingly, at 7-hr post infection, we were able to capture clusters of STAT1/STAT2 translocated cells." (PMID 36629318, 2023). "Following infection with an HIV-1–based reporter virus, single clones of PK-15 Ifnar1 k/o or PK-15 Stat2 k/o cells were assessed." (PMID 37939052, 2023). "As found in previous studies, probing whole-cell lysates by western blot showed that following VSVΔ51 infection, vanadate increases phosphorylation of STAT1 and decreases phosphorylation of STAT2." (PMID 35572196, 2022). "We observed that infection with RSV or IAV leads to the robust activation (phosphorylation) of STAT1 and STAT2 in A549 WT cells as well as IFNLR1 KO cells." (PMID 36326278, 2022). "We investigated downstream targets of interferon signaling, including STAT1, STAT2, pSTAT1 and 2, and IRF1, 7 and 9 by flow cytometry in 30 patients with COVID‐19, 17 with mild, and 13 with severe infection." (PMID 34676541, 2022). "Altogether, we conclude that despite the divergent efficacy of IFN-β induction by RSV and IAV, upon infection with any of these viruses, IFN-β is the main activator of STAT1 and STAT2 signaling." (PMID 36326278, 2022). "At 1 d post post infection, we treated the cells with 20 μM MG132 for 12 h and then analysed the STAT2 and GFPu expression levels." (PMID 34340648, 2021). "At 2 d post infection, we treated the cells with 10 μM MG132 for 24 h and then analysed STAT2 and GFPu expression." (PMID 34340648, 2021).
infection (continued). "This impaired ability of type I IFN to restrict infection has been demonstrated to be dependent on the viral antagonism of IFN-mediated phosphorylation of STAT1 and STAT2." (PMID 34338586, 2021). "The upregulation of IFITM3, STAT1, STAT2, PLSCR1, and NMI after infection was validated using western blotting and qRT-PCR." (PMID 34818332, 2021). "IFNα and IFNβ are selectively inhibited during infection by ZIKV by downstream degradation of IFN signaling molecule, STAT2." (PMID 33378361, 2020). "We further compared NoV, NoVΔB2, and NoVmB2 infection in STAT1 and STAT2 double-knockout mice (Stat1/2−/−), which are defective in the signaling by type I, II, and III interferons." (PMID 32753500, 2020). "Compared with the wild type and rFCV F9 infection groups, rFCV F9-2280 p30 infection contributed to a greater reduction in the IFN-induced STAT1 and STAT2 phosphorylation." (PMID 33075108, 2020). "Compared with the wild type and rFCV 2280 infection groups, infection with rFCV 2280 F9-p30 led to less of a reduction in the IFN-induced STAT1 and STAT2 phosphorylation." (PMID 33075108, 2020). "After infection with HMPV for 24 h, BEAS2b cells were treated with IFN to induce phosphorylation and nuclear translocation of STAT1 and STAT2." (PMID 32635475, 2020). "Innate antiviral defense genes, namely ISGs (e.g., MX1, OAS1, STAT1, STAT2, ISG15), are upregulated early in fatal infection and their expression increases dramatically throughout infection indicative of dysregulated innate immune response." (PMID 32992829, 2020). "To investigate the mechanism by which FCV 2280 infection blocks the function of IFN, we first examined the effect of FCV 2280 infection on STAT1 and STAT2 phosphorylation." (PMID 33075108, 2020). "In our study, we saw a clear increase in STAT2 levels together with IFN-induced MxA expression in DCs, which was likely due to ZIKV induced type I and type III IFNs at late time points of infection." (PMID 31673117, 2019). "Immunofluorescence double-staining was also used to determine the infection status of cells expressing STAT1, STAT2 and MX." (PMID 30939763, 2019). "The expression of STAT2, MxA and ZIKV NS5 protein was enhanced starting at 24 h after infection with the #976 virus." (PMID 31673117, 2019). "Following infection with LCMV-Cl13, DCs produce large amounts of IFN-Is, which in an autocrine manner activate STAT2 resulting in the suppression of DC expansion." (PMID 30791575, 2019). "The impaired ability of type I IFN to block infection reflected viral antagonism of type I IFN-mediated phosphorylation of STAT1 and STAT2." (PMID 28152048, 2017). "Infection alone increased the total levels of STAT1 and STAT2 protein, although notably less so at an MOI of 1 as compared to MOI 0.1." (PMID 28152048, 2017). "Mechanistically, we found infection with both contemporary and ancestral strains of ZIKV blocked phosphorylation of STAT1 and STAT2 downstream of type I IFN signaling in both human DCs and A549 cells." (PMID 28152048, 2017). "In order to activate transcriptional factors involved in innate immune responses, HeLa cells were pre-treated with recombinant human IFN-α, which activates STAT1, STAT2, and IRF9, followed by infection with WT-Ad." (PMID 26814140, 2016). "The replication of encephalomyocarditis virus (EMCV, a positive ssRNA virus) was also inhibited, five-fold by high levels of wild-type STAT1/STAT2/IRF9 or four-fold by Y701F-STAT1/STAT2/IRF9, when assayed 6 h after infection." (PMID 24065129, 2013). "In comparison to the delNS1 viruses, the IGR-39 cell interferon response was reduced after infection with wildtype NS1 expressing IVR-116 virus as indicated by decreased levels of phosphorylated STAT1 and STAT2 and alleviated MxA expression." (PMID 22563505, 2012). "The infection of IGR-39 cells with delNS1 or delNS1-IL-15, however, resulted in STAT1 and STAT2 phosphorylation and upregulation of MxA expression indicating a cellular interferon response." (PMID 22563505, 2012).
infection (continued). "JEV and Kunjin virus (a subtype of WNV) infection blocks IFN-α-induced phosphorylation of both STAT1 and STAT2 in multiple cell lines." (PMID 21379341, 2011). "Therefore we would propose that during our studies in the STAT1-/- mouse model, it is likely that infection with the virus lacking VF1 leads to the induction of a subset of ISGs during virus replication at the primary site of infection, either directly via an unknown mechanism, or via STAT2." (PMID 22174679, 2011). "In THP1 cells, physalin F inhibited SeV-induced phosphorylation of IRF3, STAT1, and STAT2 at 4 h post-infection, and had no marked effects on it at 8 h post-infection." (PMID 41599057, 2026). "However, in immunocompetent mice, NS5 cannot effectively bind mouse STAT2, resulting in a robust IFN response that suppresses ZIKV replication and infection." (PMID 40824033, 2025). "Furthermore, compared with infection with ASFV-WT, infection with ASFV-Δ4R increased the phosphorylation of STAT1 and STAT2 following IFN-β treatment." (PMID 40618140, 2025). "Furthermore, in the post-infection assays with rotavirus and C. sorokiniana, we observed a significant (p < 0.05) relative expression of SOCS3, STAT1, and STAT2." (PMID 38791551, 2024). "Indeed, infection that is capable of inducing pathogenesis in mice requires either impairing the IFN pathway, or replacing mouse STAT2 with the human gene." (PMID 38926343, 2024). "We retrieved lists of the known targets of NF-kB/p65, STAT1, STAT2, IRF2, and IRF3 and extracted from these lists genes that were differentially expressed either during infection in Dicer WT or Dicer N1 cells, or between mock-infected Dicer WT and Dicer N1 cells." (PMID 38287188, 2024). "Analysis of the effect on STAT2 phosphorylation by SFTSV infection in PK15 (pig) cells at 48 hpi showed that porcine STAT2 was phosphorylated regardless of SFTSV-infection time." (PMID 37187292, 2023). "Seven hours post infection, IFNβ produced by the first responders will diffuse to neighboring, yet nonresponding cells, thereby activating their IFNARs, followed by the subsequent translocation of ISGF3, consisting of STAT1, STAT2, and IRF9." (PMID 36629318, 2023). "Furthermore, we noted that STAT1, STAT2, IRF9 also exhibited high levels of transcription earlier in HuB20 infection than SY18." (PMID 36544767, 2022). "Immunoblotting assay results showed that PeV-A3 failed to induce STAT1, STAT2, IRF3, and NFκB p65 activation in FBS medium-maintained GBM cells; in contrast, phosphorylation of STAT1, STAT2, IRF3, and total NFκB p65 were detected in hPL-medium-maintained GBM cells with PeV-A3 infection." (PMID 35891479, 2022). "Although human STAT2 knock-in mice can recapitulate the hallmarks of human infection, this model needs further improvement as it requires a mouse-adapted ZIKV strain and exhibits low permissiveness to infection in adult mice." (PMID 36146595, 2022). "Interferon Regulatory Factors activate STAT1, STAT2, and STAT3 that stimulate the innate and acquired immune responses, mediate cellular responses to interleukin, and regulate inflammatory responses to infection." (PMID 34207861, 2021). "At 48 and 72 h post infection, C7 and C7.D29 infection resulted in a significant reduction in STAT2 in the absence or presence of IFN-α treatment, although C7.D29 reduced the protein level of STAT2 to a lesser extent." (PMID 34340648, 2021). "Compared with C7 infection, overexpression of NS5 only marginally reduced STAT2 expression." (PMID 34340648, 2021). "The primary target for NS5 is human STAT2, thus infection is generally not expected to be achieved in mice." (PMID 33946611, 2021). "While wild-type hamsters are not susceptible to infection with CCHFV, a recent study showed that STAT-2 knockout hamsters succumb to infection and can be used as a model of lethal CCHF disease." (PMID 33804381, 2021).